LDHC (lactate dehydrogenase C)
Diseases named in the same sentence as LDHC in open-access papers (continued):
Sharing a sentence is not in itself a finding about the gene and the disease.
tumor (continued). "Studies have shown LDHC promotes tumor cell invasion and migration by inducing epithelial-mesenchymal transition and the expression of matrix metalloproteinase-9 (MMP9), and this leads to a poor prognosis for tumor patients." (PMID 34852326, 2021). "Particularly, high levels of circulating LDHC in serum and tumor-derived exosomes are negatively correlated with breast cancer prognosis." (PMID 33324565, 2020). "The potential existence of an expression threshold for an effective anti-tumor response has important implications for LDHC-specific immunotherapy." (PMID 31932876, 2020). "Expression of LDHC has been reported to play a role in propagating TNBC tumor cell invasion and migration." (PMID 33324565, 2020). "Our findings suggest that targeting tumor LDHC expression could help establish a more favorable immune microenvironment, potentially enhancing responses to immunotherapy." (PMID 40108668, 2025). "Our findings suggest that targeting LDHC could enhance anti-tumor immune responses by modulating cytokine and chemokine secretion in addition to impairing immune checkpoint signaling." (PMID 40108668, 2025). "Finally, in vivo xenograft models will be crucial to validate the immunomodulatory role of LDHC within a functional tumor immune microenvironment." (PMID 40108668, 2025). "In this study, we investigated the effects of tumor LDHC expression on immune responses." (PMID 40108668, 2025). "To investigate whether LDHC expression affects immune function and impacts clinical outcomes or responses to immunotherapy, we used the Tumor Immune Dysfunction and Exclusion (TIDE) algorithm." (PMID 40108668, 2025). "We recently demonstrated that LDHC plays a vital role in regulating and maintaining tumor cell genomic integrity, suggesting that targeting LDHC could present a novel opportunity for therapeutic intervention." (PMID 39001513, 2024). "More specifically, we showed that silencing LDHC results in DNA damage accumulation, microtubule destabilization, mitotic slippage, increased polyploidy and aberrant mitosis, ultimately reducing long-term tumor cell survival." (PMID 38596293, 2024). "We investigated whether LDHC is involved in regulating genomic stability and whether it could be targeted to affect tumor cellular fitness." (PMID 34050611, 2022). "One study demonstrated the presence of tumor‐specific LDHC isoforms with defects in the structure of the catalytic domain that may result into nonfunctional, truncated splice variants." (PMID 34050611, 2022). "LDHC has been detected in various tumor types with varying levels." (PMID 36408133, 2022). "A study by Naik examined whether LDHC is involved in regulating genomic stability and whether it could be targeted to influence the cellular fitness of tumor cells." (PMID 35885460, 2022). "LDHC/LDH-C4 affects the progression of tumor development mainly by influencing glycolysis." (PMID 36408133, 2022). "However, p62-specific T cells were not able to recognize autologous ascites, autologous B cells transfected with LDHC or tumor cell lines with endogenous LDHC." (PMID 31932876, 2020). "Although LDHC expression is tightly controlled and suppressed in normal somatic tissues, it is re-expressed in various malignant tissues, making its expression highly tumor specific." (PMID 31932876, 2020). "Furthermore, we found a reduction in PD-L1 expression on the cell surface of LDHC-silenced tumor cells, suggesting that impairment of PD-L1/PD-1 signaling may contribute to improved T cell activation." (PMID 40108668, 2025). "Additionally, co-cultures with different immune cell subpopulations could offer further insight into the interactions between LDHC-expressing tumor cells and distinct components of the immune response." (PMID 40108668, 2025).
tumor (continued). "Hence, LDHC expression in tumor cells could be targeted with minimal off‐target effects, thereby affecting long‐term tumor cell survival." (PMID 34050611, 2022). "In addition, it is unclear whether the LDHC-derived peptide is processed and presented as a cognate peptide and to what extent LDHC is expressed in the patient’s tumor cells and the tumor cell lines." (PMID 31932876, 2020). "Therefore, targeting key players of lactate metabolism including LDHC could aid to re-establish anti-tumor immunity and is a largely unexplored area of research." (PMID 31932876, 2020). "This suggests that at least two CTAs—LDHC and PRAME – play vital roles in tumor development and progression by regulating anti-tumor immune responses." (PMID 40108668, 2025). "Our previous study showed that the expression of LDHC in LUAD tissues was significantly upregulated compared to normal tissues and promoted tumor progression in LUAD cells through the PI3K/Akt/GSK-3β pathway." (PMID 40270965, 2025). "A comprehensive analysis of 23 cytokines and chemokines revealed elevated levels of tumor-derived GM-CSF, IFN-γ, MCP-1 and CXCL1, alongside a decrease in IL-6 and Gal-9, further supporting the enhanced T cell activity observed following LDHC knockdown." (PMID 40108668, 2025). "Analogously with our previous observations in MDA-MB-468 cells, we found that reducing LDHC expression in BT-549 cells increased the expression of the DNA damage marker phopsho-γ-H2AX and cleaved PARP, indicating that LDHC silencing induced tumor cell death." (PMID 39001513, 2024). "We explored the expression levels of four major lactate dehydrogenase (LDHA, LDHB, LDHC, and LDHD) and found that LDHA was significantly higher expressed in tumor tissue-derived cells and LDHB was higher expressed in normal tissue-derived cells." (PMID 37795453, 2023). "Tumours from smokers or males have significantly higher transcript levels of lactate dehydrogenase C (LDHC) than non-smokers or females, implying that there is a vital role of LDHC in carcinogenesis." (PMID 35574342, 2022). "For example, Lactate dehydrogenase C (LDHC) is re-expressed in sorts of tissues of malignancy, while its expression is rigidly suppressed and controlled in normal somatic tissues, making it has a highly tumor-specific." (PMID 34852326, 2021). "Following LDHC knockdown, we observed an increase in the secretion of tumor-derived pro-inflammatory cytokines (IFN-γ, GM-CSF, MCP-1, CXCL1), a decrease in the soluble levels of tumor-derived immunosuppressive factors (IL-6, Gal-9) and reduced tumor cell surface PD-L1 expression." (PMID 40108668, 2025). "LDHC mRNA has been detected in serum and serum-derived exosomes of patients with BC, HCC, and LUAD, and the source may be related to vesicle encapsulation of tumor cells and release of necrotic tumor cells into the peripheral blood." (PMID 36408133, 2022). "Furthermore, it is likely that pre-existing high-affinity LDHC-specific T cells are partially exhausted or are only present in the tumor microenvironment and not in the ascites of patients." (PMID 31932876, 2020).
LDHC also shares sentences with these, for which no sentence is quoted: asthenozoospermia (3 papers); hyperlipidaemia (2); pancreatitis (2); pulmonary embolism (2); asthma (1); benign tumor (1); cervical cancer (1); colorectal cancer (1); COVID-19 (1); diabetes (1); dyslipidaemia (1); endothelial dysfunction (1); esophageal squamous cell carcinoma (1); gallbladder cancer (1); gastric cancer (1); Hypertension (1); kidney cancer (1); lung diseases (1); lymphoma (1); lymphopenia (1); multiple myeloma (1); mycoplasma pneumonia (1); osteoarthritis (1); paraganglioma (1); pheochromocytoma (1); Pneumocystis carinii pneumonia (1); rheumatoid arthritis (1); serous ovarian carcinoma (1); thymoma (1); thyroid cancer (1).
A further 1 disease shares a sentence with LDHC in 1 paper.